APOB (apolipoprotein B)
Diseases named in the same sentence as APOB in open-access papers (continued):
Sharing a sentence is not in itself a finding about the gene and the disease.
schizophrenia (9 papers, 2015 to 2024). A major psychotic disorder characterized by abnormalities in the perception or expression of reality. "The association between serum ApoA1 and ApoB levels and clinical symptoms in patients with schizophrenia was regulated by the presence of ApoE rs429358 polymorphism." (PMID 34930329, 2021). "For patients with schizophrenia, both ApoA1 and ApoB levels were positively associated with cognition." (PMID 34135129, 2021). "There was a significant association between ApoA1 or ApoB levels and cognition in schizophrenia, which was regulated by the ApoE rs429358." (PMID 34135129, 2021). "Furthermore, the association between ApoA1 or ApoB levels and psychopathology of schizophrenia was regulated by ApoE rs429358." (PMID 34930329, 2021). "In the unadjusted analysis, patients with SZ had markedly higher plasma TG and remnant cholesterol and lower HDL-C levels compared to controls, but similar TC, LDL-C and apoB levels, and this was observed in both men and women with schizophrenia." (PMID 39767790, 2024). "Lipid-binding proteins ApoB, ApoD, ApoF, and ApoM were reduced in patients with schizophrenia, whereas ApoE was increased." (PMID 34741130, 2022). "For example, we identified reduced levels of ApoB/D/F/M in the proteome data, which align with clinical findings of reduced lipid measurements in schizophrenia." (PMID 34741130, 2022). "A large number of studies have observed changes in the levels of ApoA1 and ApoB in patients with schizophrenia, with mixed results, such as elevated ApoA1 or ApoB, which can be used as biomarkers of schizophrenia as well as decreased ApoA1 or ApoB." (PMID 34930329, 2021). "On the one hand, numerous studies have observed the mixed changes in ApoA1 and ApoB levels in patients with schizophrenia, such as an increase in ApoA1 or ApoB and reduction of ApoA1, or ApoB." (PMID 34135129, 2021). "We speculated that ApoE polymorphism rs429358 may be involved in the development of schizophrenia and further the relationship between the clinical symptoms and the ApoA1 or ApoB levels in patients with schizophrenia." (PMID 34930329, 2021). "Our study found that ApoA1 and ApoB levels were positively associated with PANSS negative symptoms in patients with schizophrenia." (PMID 34930329, 2021). "This study found that the levels of ApoA1 and ApoB were negatively associated with negative symptoms of patients with schizophrenia." (PMID 34930329, 2021). "First, owing to the cross-sectional study design, the causality between ApoE rs429358, ApoA1 and ApoB levels, clinical symptoms in patients with schizophrenia was not directly presented." (PMID 34930329, 2021). "However, the serum ApoA1 and ApoB levels were positively correlated with the degree of cognitive function in patients with schizophrenia, indicating that serum ApoA1 and ApoB levels may be biomarkers of general cognitive function in schizophrenia patients." (PMID 34135129, 2021). "Reassuringly, many recapitulated genes are well-established for the traits, such as CACNA1C for schizophrenia, TCF7L2 for T2D, APOB for lipids, and STAT4 for autoimmune diseases." (PMID 33990562, 2021). "ApoA1 is the main protein component of HDL, and a biomarker of cardiovascular disease, while ApoB is the main protein including plasma chylomicrons, very-low-density lipoprotein (VLDL) and LDL, which can be used as a biomarker of schizophrenia." (PMID 34135129, 2021). "A significant correlation between PANSS negative symptoms and ApoA1 levels (p = 0.048) or ApoB levels (p = 0.001) was found in patients with schizophrenia, which was also confirmed by linear regression analyses (p = 0.048 vs. p = 0.001)." (PMID 34930329, 2021). "Our study found that ApoE rs429358 genotype groupings had a significant effect on the relationship between serum ApoA1 or ApoB levels and negative symptoms of schizophrenia." (PMID 34930329, 2021).
schizophrenia (continued). "These consistent results may suggest that the impacts of ApoA1 and ApoB levels on cognitive function may not be affected by schizophrenia." (PMID 34135129, 2021). "Thus, ApoE genotype may play a role in conferring negative symptoms in schizophrenia by affecting ApoA1 or ApoB levels." (PMID 34930329, 2021).
systemic lupus erythematosus (9 papers, 2010 to 2025). An autoimmune multi-organ disease typically associated with vasculopathy and autoantibody production. "Most published results have revealed variations in the association of serum/plasma levels of malondialdehyde (MDA), apolipoprotein B (ApoB), and oxidized low-density lipoprotein (OxLDL) and systemic lupus erythematosus (SLE)." (PMID 39104552, 2024). "This study was performed to establish MDA, ApoB, and OxLDL levels in systemic lupus erythematosus (SLE) patients." (PMID 39104552, 2024). "Despite the LDL levels being similar in our study groups, ApoB concentration was higher in our lupus patients compared to healthy subjects." (PMID 27004558, 2016). "An exception is systemic lupus erythematosus (SLE), where the pattern of dyslipidemia is similar to the general population with a high cardiovascular risk – high level of LDLc, total cholesterol and apoB and low levels of HDLc." (PMID 32375792, 2020). "Patients with systemic lupus erythematosus disease activity index (SLEDAI) ≥8 of SLE had higher MDA and ApoB levels, whereas SLE patients with SLEDAI <8 showed significantly higher ApoB levels." (PMID 39104552, 2024). "However, follow up of disease activity over 3-7 years (mean=4.9 years) revealed that the baseline ApoB:ApoA1 ratio correlated positively with average longitudinal SLEDAI-2000 score and negatively with longitudinal Lupus Low Disease Activity State (LLDAS)." (PMID 33640328, 2021).
bladder cancer (8 papers, 2020 to 2025). "It is interesting that the presence of ApoB in urinary extracellular vesicles is a biomarker for malignant bladder cancer." (PMID 37686366, 2023). "The detection of ApoB plays a vital role in the diagnosis and discrimination of the grade of bladder cancer." (PMID 36506554, 2022). "A recent study proposed the role of BKPyV in the development of bladder cancer via the anti-viral apolipoprotein B mRNA editing enzyme catalytic polypeptide (APOBEC)-mediated damage of the urothelial genome." (PMID 36123699, 2022). "High levels of APOB in urine were proposed as a potential marker and a prognostic factor for bladder cancer." (PMID 31963743, 2020). "The experiments provide a new insight into the efficacy of novel antimicrobial strategy, i.e., an antimicrobial peptide identified in human apolipoprotein B, alone or in combination with antibiotics, in fighting clinically isolated bacteria from bladder cancer patients after radical cystectomy." (PMID 35743833, 2022).
diabetic kidney disease (8 papers, 2020 to 2025). Progressive kidney disorder caused by vascular damage to the glomerular capillaries, in patients with diabetes mellitus. "In the unadjusted Model 1, both ApoB (0.8–1.2 g/L) and ApoB (>1.2 g/L) showed significant associations with Diabetic Nephropathy (DN) (P < 0.05)." (PMID 40379620, 2025). "Few studies have investigated the association of apolipoprotein B (ApoB) with the progression of diabetic kidney disease (DKD) and the risk of renal replacement therapy (RRT)." (PMID 32242489, 2020). "Few studies have investigated the association between ApoB and the decline in kidney function in diabetic kidney disease (DKD) patients." (PMID 32242489, 2020). "This study aimed to investigate the role of Apolipoprotein B (Apo B) in diabetic nephropathy (DN) from epidemiological and genetic perspectives." (PMID 40379620, 2025).
dysbetalipoproteinemia (8 papers, 2017 to 2025). "With the exception of type III hyperlipoproteinemia, apoB48 particles contribute minimally to total apoB, which is determined by the sum of VLDL and LDL particles." (PMID 33598387, 2021). "Only dysbetalipoproteinemia (FLL Type III) could not be identified by this scheme, as this requires apoB measurement." (PMID 41226954, 2025).
Glucose intolerance (8 papers, 2013 to 2023). Glucose intolerance (GI) can be defined as dysglycemia that comprises both prediabetes and diabetes. "Interestingly, only obese women of phenotype D show aggravated glucose intolerance as indicated by poorer 2 h glucose levels following OGTT, and significantly reduced ApoA-1 levels coupled with increased ApoB:ApoA1 ratios compared to lean counterparts." (PMID 33635862, 2021).
kidney damage (8 papers, 2017 to 2025). "The uptake of ApoB by glomerular macrophages causes it to be deposited in the mesangial area of ​​the glomerulus, leading to glomerular hypertrophy and increasing transforming growth as well as the level of TGF-β, which in turn cause kidney damage." (PMID 34627286, 2021). "Lp(a), ApoA-Ι and ApoB are common and easily available clinical indicators that are correlated with the prevalence of not only CHD but also kidney damage." (PMID 34627286, 2021). "This includes KNG, an important pro-inflammatory and pro-oxidant factor belonging to the kallikrein-kinin-system that regulates cardiovascular and renal function; Cystatin-C, a recognized biomarker of kidney damage, MetS and CVD predictor; as well as the previously cited ApoB." (PMID 36829843, 2023). "Serum apoB/A-I ratios may not be helpful to predict CAC in participants with mild RI (90–60 mL/min/1.73 m2 of eGFR), although these participants did not have CKD, which is defined as impaired kidney function (less than 60 mL/min/1.73 m2 of eGFR) or evidence of kidney damage." (PMID 28957410, 2017).
anemia (7 papers, 2015 to 2025). A reduction in the number of red blood cells, the amount of hemoglobin, and/or the volume of packed red blood cells. "BMI was inversely associated with ApoB, iron deficiency anemia, hernia, and total testosterone in men, while positively associated with these traits in women." (PMID 40498079, 2025). "In model II, patients with rivaroxaban anemia, ABCB1 rs3842 variant homozygote (CC) and APOB rs13306198 variant allele (AG, AA) had a higher risk of bleeding risk." (PMID 36145636, 2022). "Therefore, we constructed a risk scoring system using both demographic factors and genetic factors, which remained in Model II; overdose, rivaroxaban, anemia, ABCB1 rs3842, APOB rs693 and APOB rs13306198 were taken as 2, 1, 1, 1, 3 and 1 point, respectively." (PMID 36145636, 2022).
Autoimmunity (7 papers, 2021 to 2024). The occurrence of an immune reaction against the organism's own cells or tissues. "ApoB autoimmunity is associated with cardiovascular risk factors in humans." (PMID 39765749, 2024). "Our data is a resource for future studies investigating vaccination strategies with ApoB to modulate proatherogenic autoimmunity." (PMID 36684560, 2022).
malnutrition (7 papers, 2007 to 2024). Inadequate nutrition resulting from poor diet, malabsorption, or abnormal nutrient distribution. "The paradoxical association between ApoB and worse prognosis was mainly mediated by the effect of bilirubin and underlying malnutrition." (PMID 35146010, 2022). "The decreased level or impaired function of apoB connected with the APOB gene mutation also lead to malnutrition and deficiencies in fat soluble vitamins (A and E)." (PMID 32093271, 2020). "Notably, they also discovered that low ApoB levels at baseline were related to a high risk of a poor prognosis, possibly due to malnutrition." (PMID 38789961, 2024). "In the present study, the prevalence of mild, moderate, severe malnutrition in the low ApoB group (<65 mg/dL) was 67.90, 20.43, and 1.49%, respectively." (PMID 35146010, 2022). "Since there was a tight connection between ApoB and total cholesterol, which is an evaluation index for nutritional status, low ApoB may also indicate potential malnutrition." (PMID 35146010, 2022).
polycystic ovary syndrome (7 papers, 2017 to 2025). A disorder that manifests as multiple cysts on the ovaries. "Apolipoprotein A-IV and apolipoprotein B-100 are closely related to glucose and lipid metabolism, IR, and polycystic ovary syndrome." (PMID 34646426, 2021). "This study was a secondary analysis of the Acupuncture and Clomiphene for Chinese Women with Polycystic Ovary Syndrome trial (PCOSAct), and 957 subjects with available ApoB and ApoA1 measurements were included." (PMID 35069437, 2021). "The Chinese study demonstrated that the ratio of apolipoprotein B to apolipoprotein A1 is a good predictive indicator of MetS and pre-MetS in young women with polycystic ovary syndrome." (PMID 32668760, 2020).
preeclampsia (7 papers, 2013 to 2025). Preeclampsia is a hypertensive disorder of pregnancy that is characterized by new-onset hypertension with proteinuria presenting after 20 weeks of gestation, and depending on mild or severe forms may initially present with severe headache, visual disturbances, and hyperreflexia. "Numerous studies have shown that ApoB levels were significantly increased in the blood of patients with preeclampsia (P < 0.05)." (PMID 40717981, 2025). "In this study, we observed that ApoB expression was downregulated in the placentas of preeclampsia mice but was upregulated following treatment with SA pairs." (PMID 40717981, 2025). "ApoB levels were increased in preeclampsia (PE), fetal growth restriction (FGR), and PE + FGR in comparison to normal pregnancies." (PMID 39590866, 2024). "In a prospective cross-sectional case control study on maternal and fetal lipid levels in preeclampsia and fetal growth restriction, the authors have demonstrated not only that maternal TG levels are increased in preeclampsia but also that fetal TG and ApoB are elevated in these conditions." (PMID 32000699, 2020). "The literature supports consistent changes in ApoB, Sod2, and EML4 trends with the results of this study, confirming a potential relationship between the therapeutic effects of SA on preeclampsia and the PI3K/Akt/eNOS pathway." (PMID 40717981, 2025).
prostate carcinoma (7 papers, 2018 to 2025). A carcinoma that arises from epithelial cells of the prostate gland. "ApoA was associated with higher fatal prostate cancer risk overall, but ApoB was associated with higher fatal prostate cancer risk in Black men only)." (PMID 39200296, 2024). "There are limited published prospective data on ApoA-I and ApoB in relation to prostate cancer risk." (PMID 32963348, 2020). "Although APOB is frequently identified in blood EVs in various studies, its sorting during EV biogenesis and regulation during the acquisition of the Warburg phenotype, especially in prostate cancer, remain unknown." (PMID 40089067, 2025). "Neutrophil–lymphocyte ratio, platelet–lymphocyte ratio, lymphocyte- monocyte ratio, and apolipoprotein B were lower and apolipoprotein A-I was higher in the prostate cancer group than in the benign lesions group but not significantly (P > 0.05)." (PMID 33251229, 2020).
xanthoma (7 papers, 2014 to 2025). A non-neoplastic disorder characterized by a localized collection of histiocytes containing lipid. "Hence, when a patient presents with clinical features, such as palmar xanthomas, or a history consistent with Type III, additional testing, such as apoB or agarose gel electrophoresis, will be necessary to confirm the diagnosis." (PMID 34838008, 2021). "Although a higher level of total cholesterol and LDL-c is reported in patients with xanthoma than in those without xanthoma, in our study, LDL-c levels, ApoB and oxidized LDL were similar in the two groups of patients." (PMID 35897824, 2022).
asthma (6 papers, 2016 to 2025). "In contrast, triglycerides, LDL-cholesterol, and ApoB are associated with unfavorable asthma outcomes." (PMID 38999820, 2024). "In another ICS response study in admixed children from GALAII and SAGE cohorts with asthma, rs5995653 SNP related to apolipoprotein B mRNA-editing catalytic polypeptide 3 (APOBEC3)B and APOBEC3C genes was associated with a protective effect against asthma exacerbations." (PMID 37228580, 2023). "Apolipoprotein B, linked to type 2 inflammation, may enhance systemic inflammatory conditions, but this has not been studied in asthma." (PMID 41216128, 2025). "Total cholesterol, LDL-cholesterol, and ApoB values showed a significant correlation with FeNO in patients diagnosed with asthma by functional tests, without a correlation in those diagnosed by the specialist." (PMID 38999820, 2024).
cognitive decline (6 papers, 2012 to 2025). "Previous research has shown a higher ApoB/ApoA1 ratio indicates a higher risk of cognitive decline in the future." (PMID 39484667, 2022). "In the Sydney Memory and Aging Study, a lower ApoA1 level and higher ApoB/ApoA1 ratio were associated with a greater risk of cognitive decline." (PMID 36247924, 2022). "Lower ApoA1, ApoA2 and ApoH levels, and higher ApoB/ApoA1 ratio, increased the risk of cognitive decline over two years in cognitively normal individuals." (PMID 22701550, 2012). "In summary, participants with lower ApoA1, ApoA2, ApoH levels or higher ApoB/ApoA1, at Wave 1 had a higher risk of future cognitive decline." (PMID 22701550, 2012). "In a cohort after 15-year follow-up, higher level or atherogenic lipoproteins including ApoB and LDL cholesterol were associated with greater cognitive decline in executive function." (PMID 36247924, 2022). "ApoB from cerebrospinal fluid sample was identified as an important marker for tau pathology and cognitive decline, which reinforces the need for considering apolipoproteins in clinical practice, and these findings may also be useful for designing more effective drug interventions." (PMID 36247924, 2022).
diabetic retinopathy (6 papers, 2014 to 2023). "On the other hand, serum levels of ApoB, ApoC3 and the ApoA1 to ApoB ratio showed positive correlations with diabetic retinopathy." (PMID 35628887, 2022). "By contrast, the serum levels of ApoB, ApoC3, and the ratio of ApoA1 to ApoB had positive correlations with diabetic retinopathy." (PMID 33213461, 2020). "Lower apoAI and higher apoB and apoB/AI levels, biomarkers for diabetic retinopathy, are involved in the pathogenesis of cardiovascular diseases, which is a risk factor for AMD." (PMID 25238063, 2014). "Moreover, ApoB itself has also been confirmed to have the positive relationship with the severity of diabetic retinopathy." (PMID 33213461, 2020). "By the immunostaining research, the intracellular level of ApoB was increased within the LDL particle during the promotion of diabetic retinopathy, suggesting that ApoB could be used as a novel biomarker of diabetic retinopathy." (PMID 33213461, 2020). "Moreover, the circulating levels of HDL-bound apoprotein A1 and apolipoprotein B (present in LDL, lipoproteins (a), VLDL and chylomicrons) were observed to be more potent predictors of diabetic retinopathy than the traditional lipid layers." (PMID 35628887, 2022). "The ApoB, being the main apolipoprotein in VLDL and LDL particles, was found to be involved in atherosclerosis and coronary diseases and correlated with the advancement of diabetic retinopathy." (PMID 35628887, 2022). "In addition we found ALDH1A1, RBP4, APOB, APOA1, RBP1, APOE and RHO genes enriched in retinoid metabolic process as unique GO in diabetic retinopathy." (PMID 28761062, 2017). "In type 2 diabetes patients with or without diabetic retinopathy, multivariate logistic regression analysis showed that APOC2/APOC3 and APOB/non‐HDL cholesterol, as well as APOE/APOC2, were independently related to the risk for the occurrence and severity of diabetic retinopathy." (PMID 37448184, 2023).